LAMP1 (lysosome associated membrane protein 1)
Diseases named in the same sentence as LAMP1 in open-access papers (continued):
Sharing a sentence is not in itself a finding about the gene and the disease.
infection (continued). "The early phagosome marker, EEA1, and the late phagosome marker, lysosomal-associated membrane protein 1 (LAMP-1), showed a consistently increased ratio of colocalization with FITC-labeled Mtb-containing phagosomes throughout H37Ra or H37Rv infection." (PMID 29755479, 2018). "Infection of NHBE cells with continuously exposed NTHI results in a punctate LAMP1 staining pattern that appears to be centrally located within the cell." (PMID 30209128, 2018). "Intracellular trafficking of Salmonella through the endocytic pathway and acquisition of the late endosomal marker LAMP1 is another measure of Salmonella maturation during MDM infection." (PMID 29538403, 2018). "Here we identify 3.3, a small molecule that inhibits LASV infection by targeting lysosome-associated membrane protein 1 (LAMP1), which binds to the LASV glycoprotein (GP) and promotes virus membrane fusion and infection." (PMID 30265711, 2018). "The colocalization rates of LAMP1 with wild-type bacteria were approximately 50.7 and 36.3% under the infection of FY26 in HD11 macrophages at 2 and 4 hpi, respectively (P < 0.01)." (PMID 29719540, 2018). "It is suggested that PPRV infection induced the fusion of autophagosomes with acidified LAMP1-positive lysosomes and thereby strengthened the degradation of autophagy substrates." (PMID 30067475, 2018). "In Lamp1 KO 293T cells, entry and infection by both MLV and VSV pseudovirus particles expressing LASV GPC occur at ~20 to 30% of the level seen in WT cells." (PMID 29295909, 2018). "The rates of LAMP1-positive GcAV in Bcl-xL KO cells were higher than those in wild-type cells at all time points of infection, suggesting that the promotion of GcAV-lysosome fusion in Bcl-xL KO cells dose not only reflect the increased number of invaded GAS." (PMID 28085926, 2017). "In THP-1 cells, using dual staining, we found that at 3 hours post-infection ~50% of LC3-positive LdCVs were also positive for LAMP-1." (PMID 28317932, 2017). "Nuclear translocation of IRF-1 was markedly reduced over the first 3 days of infection in macrophages treated with siRNA to MyD88, suggesting MyD88 is conveying Mav-induced responses from the LAMP1+ phagolysosome." (PMID 28806745, 2017). "At later times post-infection (12 h), tachyzoites encircled by LAMP-1 exhibited morphology that suggested they were undergoing degradation." (PMID 29036202, 2017). "The transition of L. monocytogenes from the host cytosol to LAMP1+ compartments correlated with a decrease in ActA expression during long-term infection." (PMID 29190284, 2017). "Next, to examine the influence of Bcl-xL on the autophagosome-lysosome fusion, we observed co-localization of LAMP1 with GcAV at 1, 2, 4 and 6 hours post infection." (PMID 28085926, 2017). "After infection of mCherry‐galectin‐3 stable transformant cells with U. parvum for 3 hr, galectin‐3 signals colocalized with LAMP‐1." (PMID 28088841, 2017). "The few Δhly bacteria remaining after 3 days of infection were isolated bacteria enclosed in LAMP1+ compartments." (PMID 29190284, 2017). "Quantification over time demonstrated that, contrary to live Mav, PFA-killed Mav was retained in LAMP1+ phagolysosomes throughout the 3-day infection and significantly different from live Mav 3 days post infection." (PMID 28806745, 2017). "A typical marker of early BCVs, LAMP-1, is retained in late BCVs even 24 h after infection in the presence of low doses of nocodazole or paclitaxel and in the presence of different amounts of rTcpB." (PMID 29184543, 2017). "At 24 h after infection, the vacuoles show only the late endo/lysosomal markers Rab-7 and LAMP-1, suggesting maturation from early to late endosomes." (PMID 27322323, 2016). "To this end, we determined the number of LAMP-1-positive Brucella-containing vacuoles (BCVs) at 4 and 24 h post-infection of RAW264.7 cells with the pyk mutant and the S2308 strain." (PMID 27561260, 2016).
infection (continued). "Shortly after infection, these vacuoles also contain markers pertaining to early and late endosomes, Rab-5 and Rab-7, respectively, and LAMP-1 colocalization, a marker for lysosomes, even though VacA escapes lysosomal degradation." (PMID 27322323, 2016). "Time-lapse videomicroscopy revealed a concomitant accumulation of mCherry-2*ML1N and LAMP1 on the SCV from 60 min post-infection (p.i.)." (PMID 27625994, 2016). "We either used DsRed transgenic parasites and Bodipy 493/503 labeling to perform time-lapse live cell imaging at different times post-infection or WT parasites and simultaneous LAMP1 or LPG and Bodipy 493/503 labeling of fixed cells." (PMID 26871576, 2016). "At day 3 post-infection, samples were fixed and stained for Coxiella and LAMP1 to visualize CCV size." (PMID 28002452, 2016). "The co-localization between punctate GFP-LC3-expressing cells and lysosomal-associated membrane protein 1 (LAMP1) was also observed, indicating that poliovirus induces autophagosome maturation during infection." (PMID 26828514, 2016). "Fluorescence microscopy imaging of WT macrophages showed that ~40% of PVs stained strongly for LAMP1/2 at 8 h post-infection, and this increased to ~80% by 72 h." (PMID 27280707, 2016). "Most RFP puncta were positive for GFP (i.e., yellow puncta after merging of the images) and only a few of them colocalized with LAMP1 (i.e., purple puncta after merging of the images) at 24 hours post-infection." (PMID 25807108, 2015). "The presence of LAMP1 on SCVs at 16 hours post-infection was examined and illustrated by confocal microscopy." (PMID 26268777, 2015). "This study confirmed that wild type B. ovis escapes from LAMP1+ compartment at early time points post infection, whereas the B. ovis vacuole acquires calreticulin marker, which is associated with intracellular multiplication at later time points." (PMID 26366863, 2015). "At 20 and 80 min post-infection, cells were washed, fixed with paraformaldehyde, and stained with anti-Lamp1 antibody, a marker for lysosomal fusion." (PMID 26495854, 2015). "In contrast, co-localization of the wild-type strain with LAMP-1 was only around 24% after 1 h and remained in the same range throughout the infection (20% and 22%, after 4 h and 10 h, respectively)." (PMID 24453979, 2014). "In macrophages, we found that virtually all internalized bacteria became LAMP-1 positive within 1 h of infection, indicating that SCVs formed efficiently in both WT and FAK-deficient cells." (PMID 24901456, 2014). "At late time points after infection, typically 7 to 8 h p.i., microcolonies of sifA Salmonella started to lose the continuous LAMP1-GFP-positive compartment." (PMID 25522146, 2014). "At 30 minutes post-infection, 22±11% of phagosomes containing T. whipplei colocalised with Lamp-1; this percentage increased progressively and reached 61±8% at 4 hours post-infection." (PMID 24586722, 2014). "We observed that at 8 h after infection with Salmonella WT all double membrane type 2 SIT were positive for LAMP1-GFP." (PMID 25254663, 2014). "At 96 h post-infection these mutants were observed as single bacteria inside of LAMP1-positive vacuoles." (PMID 25080348, 2014). "For fluid tracer experiments, HeLa LAMP1-GFP cells were pulse-chased with BSA-Rhodamine-gold at various times prior or after the infection with Salmonella WT and analyzed by live cell imaging." (PMID 25254663, 2014). "In wild-type females, E. coli were detected within enlarged Rab7-GFP positive phagosomes at 15 to 45 minutes after infection; and were also observed in enlarged Lamp1-GFP positive phagolysosomes at 45 minutes." (PMID 24709696, 2013). "Macrophages infected with the parental strain showed that 40±0.2% of BcCVs acquire LAMP-1 by 4 h post-infection, as we have previously demonstrated." (PMID 22848580, 2012). "Amastigotes were initially lodged in tight-fitting LAMP1-positive PVs in the first hours of infection (2 h post-infection)." (PMID 22348167, 2012).
infection (continued). "We examined 194 metacyclic promastigote- and 340 amastigote-containing PVs and quantified LAMP-1 recruitment at 1 h and 24 h after infection." (PMID 21552562, 2011). "Twenty-four hours after infection was initiated, many promastigote-induced PVs were LAMP-1+, indicating fusion with late endosomes/lysosomes." (PMID 21552562, 2011). "As predicted by literature reports, after 24 h, PVs initiated by amastigote infection were mostly LAMP-1+." (PMID 21552562, 2011). "During infection, punctate LC3 also co-localized with lysosomal-associated membrane protein LAMP1, a marker of late endosomes and lysosomes." (PMID 21994795, 2011). "To assess the effect CLDC, MPF and CLDC+MPF had on SchuS4 phagosomal escape we next examined co-localization of SchuS4 with LAMP-1 in treated mouse and human macrophages 24 h after infection by microscopy." (PMID 20523903, 2010). "We also observed that the mCAT1 protein and the LAMP1 are in close proximity in the infected cell and the colocalization increases actively with infection." (PMID 21151933, 2010). "The average distance from the nucleus of LAMP1+ SCVs containing wild type bacteria was 2.19 μm at 10h post infection and increased to 7.86 μm by 24 h after infection." (PMID 20140193, 2010). "The colocalization co efficiency of the total blue (LAMP1) with red (mCAT1) that has given rise to magenta colour is around 26% at 4 h of infection." (PMID 21151933, 2010). "The percentage of LNT contacting LAMP1-vesicles was reduced compared to cells infected with the wild-type strain, especially at early times of infection." (PMID 20664790, 2010). "During infection of MEFs, WT Mm escaped from phagosomes and polymerized actin, were ubiquitinated, and ubiquitinated WT Mm were sequestered into LAMP-1 positive compartments, thus recapitulating the major events in Mm infection of macrophages." (PMID 19436699, 2009). "All L2 cysteine mutant virions were non-infectious despite exhibiting normal cell binding, internalization, and trafficking to LAMP-1 positive lysosomes by 8 h post infection." (PMID 19214230, 2009). "Campos and Ozbun observed indistinguishable cell surface binding and uptake into endosome/lysosomes co-incident with LAMP-1 at 8 h post infection." (PMID 19860897, 2009). "Mtb phagosomes obtained one hour after infection contained similar or greater levels of early endosomal markers to those seen in the LAMP-1+/HLA-Ilo/− magnetic bead population." (PMID 19360129, 2009). "At 1.5 hours after infection, only 6% of Lp01 colocalized with LAMP-1 vs. 57% of the dotI mutant (P<0.001)." (PMID 18431493, 2008). "Approximately 5 h after infection, more than 90% of the parasites can be co-stained with antibodies specific for the phagolysosomal marker LAMP-1." (PMID 19087356, 2008). "As SipA localizes to LAMP1-rich SCVs independently of F-actin during infection, we visualized LE/Lys distribution in cells expressing SipA, SipA-N, and SipA-C." (PMID 18005682, 2007). "Instead, it resulted in higher levels of LAMP1-positive (membrane-bound) Listeria compared to the WT strain at later timepoints, due to the failure of ΔplcB Listeria to escape from double-membrane vacuoles during secondary infection (Fig. EV4J–L)." (PMID 41266655, 2026). "Conidia were found in actin- and Lamp1-positive vesicles already after one hour of infection." (PMID 41604383, 2026). "At 3 hours post-infection bacteria were also found to colocalize with LAMP1 in addition to Rab-5." (PMID 41499635, 2026). "Furthermore, we observed entrapment of HEV capsid and colocalisation with the genome in LAMP1-positive lysosomes 24 h post-infection when treated with E64, suggesting unsuccessful uncoating upon cathepsin inhibition." (PMID 40571699, 2025). "The infection of HMDMs obtained after stimulation with M-CSF, which induces macrophage polarization into anti-inflammatory phenotypes, demonstrated that the bacteria also remained within LAMP1 compartments up to 44 hpi." (PMID 40037395, 2025).
infection (continued). "However, a large number of colocalization of FTN_0096 mutant with LAMP-1was observed in 70−79% of the cells at 2, 6, 12, and 24 h post-infection, indicating significant colocalization of the mutant with LAMP-1." (PMID 40748985, 2025). "We show herein that HAdV-D37 infection of both immortalized and primary corneal epithelial cells is associated with HMGB1 acetylation, CRM1-dependent nuclear-to-cytoplasmic translocation, and LAMP1-mediated release of into cell supernatants, in contrast to infection of the same cells by HADV-C5." (PMID 40367285, 2025). "However, the colocalization of pseudovirus with Rab7 was markedly elevated in STX6 knockdown cells at both 30 and 90 min post-infection, whereas its colocalization with LAMP1 was modestly reduced at the same time points." (PMID 40277356, 2025). "We again found that GAS was initially located in phagosomes, as indicated by EEA-1 staining, which was followed by rapid bacterial colocalization with the mature lysosomal marker LAMP-2 within the first 15 min of infection, similar to the colocalization dynamics observed with LAMP-1 staining." (PMID 38722166, 2024). "The expression of LAMP1, a marker of lysosomes, was measured during infection." (PMID 39369445, 2024). "Having determined the requirements of DRAM1 for Mm’s colocalisation with LysoTracker, LC3 and LAMP1, we wished to understand whether this role of DRAM1 in Mm vesicle trafficking impacts the susceptibility of RAW 264.7 macrophages to Mm infection." (PMID 36980169, 2023). "The cells were then washed and further incubated in the presence of a bacteriostatic concentration of Polymyxin B. At 6, 24, or 48 h points post-infection bacterial colocalization with late endosomal (LAMP-1) and lysosomal (cathepsin D) markers was investigated." (PMID 38011105, 2023). "A positive feedback loop may thus be formed during the infection process: infection leads to deglycosylation of LAMP1 and LAMP2 and subsequent lysosomal dysfunction, while lysosomal dysfunction further enhances viral entry into the cell." (PMID 38057804, 2023). "Thus, to investigate where intracellular UPEC were housed in BECs 24 h p.i., we probed UPEC-infected BECs with antibodies against LAMP1, at different time-points following infection." (PMID 37167325, 2023). "STM WT harboring the reporter was used for infection of HeLa LAMP1-GFP cells." (PMID 36457851, 2022). "LI may require the more hydrolytic low-pH of late endosomes to fuse in a LAMP1-independent manner and, therefore, have a far lower infection efficiency." (PMID 35730904, 2022). "Further, transport of reovirus to LAMP1-positive compartments prevents efficient infection." (PMID 35320319, 2022). "We classified the observed phenotypes in 4 categories, (i) noninvasive, (ii) capable of entry and survival, (iii) capable of replication and visible by the formation of LAMP1-positive bacterial clusters, and (iv) hyperinvasive, with a rate of infection equivalent to the A. baumannii ABC141 strain." (PMID 35103489, 2022). "This novel approach provided unprecedented details regarding the dynamics of LASV fusion pores and revealed that ectopic expression of human LAMP1 in avian cells leads to a marked acceleration of fusion but modestly increases the likelihood of complete pore dilation and infection." (PMID 35969633, 2022). "This in turn suggests that CAB2-GFP and CAB2ΔvopC-GFP in the dispersed morphology are also replicating cytosolically, consistent with the canonical V. parahaemolyticus T3SS2-mediated infection cycle, as they too lack LAMP-1 staining around the periphery of the bacterial growth." (PMID 35862776, 2022). "Ectopic expression of LAMP1-WT or LAMP1-d384 resulted in a modest, ~3-fold, increase in virus fusion and single-cycle infection of both A549 and DF-1 cells, although hLAMP1 expression somewhat more strongly enhanced infection of DF-1 cells compared to A549 cells (for raw data)." (PMID 35969633, 2022).
infection (continued). "Importantly, eGFP-expressing C. burnetii isolated from blood samples on which infected ticks fed were effectively internalized by U2OS human epithelial cells upon infection, and developed the typical, LAMP1-positive intracellular replicative vacuole." (PMID 33406079, 2021). "The enhancing effect of LAMP1 knock down on IAVpp infection may be related to altered virus transport pathways and/or to changes in acidity of endosomal compartments." (PMID 34492091, 2021). "However, Ms3091-eGFP pretreated with pre-immune IgG showed a relatively lower number of LAMP-1 positive signals at 24 h post-infection, supporting Ms3091-eGFP escape from phagosome." (PMID 33042041, 2020). "Infection of HeLa cells with the remainder of the multiple-effector deletionmutants with different combinations of deleted effectors reveals that themechanism of LAMP1+-tubule extension is indeed very intricate." (PMID 32584855, 2020). "Therefore, it is of interest to understand the mechanism of action of the host LAMP1 with LASV protein during infection." (PMID 32974605, 2020). "Finally, LAMP1 staining throughout infection show that lysosome dynamics around the PVM is distinct in the presence or absence of C4." (PMID 33214643, 2020). "Consistent with previous reports, LVS tagged with a fluorescent reporter (GFP-LVS or mCherry-LVS) was phagocytosed by macrophages and began to escape from EEA1+ or LAMP1+ phagosomes within 1 to 2 h of infection (illustrating partial LVS colocalization with LAMP1 by 4 h after infection)." (PMID 32694562, 2020). "The low frequency of LAMP1+-tubule extension observed in multiple-effectordeletion mutants lacking ΔsseFG may be directly related to the roleof SseF and SseG during infection." (PMID 32584855, 2020). "Although the Δslt mutant did not colocalize with acidic organelles stained with LysoTracker during the early stages of infection (0.5 h–2 h), the mutant colocalized with the autophagosome marker LC3 and the lysosome marker LAMP-1 during the late stages of infection (12 h–48 h after infection)." (PMID 31877174, 2019). "Approximately 2–6 hours post infection, the phagosome fuses with lysosomes, delivering lysosomal membrane proteins, including LAMP1 (Lysosome-associated membrane glycoprotein-1) and v-ATPase, and lysosomal enzymes such as acid phosphatases and cathepsins to the phagosome." (PMID 31869379, 2019). "In addition to LAMP-1, other regulators could also potentially contribute to regulate the fusion; Rab5A and Rab22A have been found to be associated with the stimulation of the maturation of phagosomes containing either Listeria or Mycobacteria during early infection." (PMID 30186773, 2018). "A low level of Lamp1 supports robust LASV GPC-mediated infection." (PMID 29295909, 2018). "This suggests that by day 6, inefficient viral entry in Lamp1−/− mice may have afforded an opportunity for the immune system to clear the infection." (PMID 29295909, 2018). "After infection, cells were stained with lysosomal LAMP1 antibody." (PMID 30050511, 2018). "The lower colocalization of wild-type FY26 with LAMP1-positive phagolysosomes during its infection suggested that wild-type FY26 could escape from phagolysosomes and enter the cytosol." (PMID 29719540, 2018). "Infection in Lamp1 KO cells was, indeed, more sensitive to the neutralizing effects of NH4Cl." (PMID 29295909, 2018). "Infection with transiently restricted NTHI changes LAMP1 distribution." (PMID 30209128, 2018). "Interestingly, we also found that Leishmania-PV acquires Lamp1 and CathepsinD after 24 h of infection in human macrophages as observed previously in mouse macrophages." (PMID 28650977, 2017). "Furthermore, the late endosome marker Rab7, LAMP‐1, and recycling endosome marker Rab11 colocalized with U. parvum 3 hr after infection." (PMID 28088841, 2017). "However, we unexpectedly observed delayed acquisition of LAMP1 with ~10% of LdVCs positive at 3 to 4 hours post-infection." (PMID 28317932, 2017).